CTSB (cathepsin B)
Diseases named in the same sentence as CTSB in open-access papers (continued):
Sharing a sentence is not in itself a finding about the gene and the disease.
tumor (continued). "Moreover, the conjugated PTX could be released specifically triggered by cathepsin B, which was confirmed from the HPLC, and the released PTX decreased the tumor cell viability, damaged the microfilaments (α/β tubulin and pan‐actin), and induced apoptosis." (PMID 37908735, 2023). "Moreover, cathepsin B levels in the TME are associated with the effect tumor cells have on non-malignant cells in the TME; i.e., their reaction to the acidic environment causes the release of cathepsin B into the intercellular area." (PMID 37568601, 2023). "We conclude that targeting the activity or expression of CTSB may be important for treating tumor and non-tumor diseases." (PMID 37576397, 2023). "Additionally, complete MMAE release could be reached after incubation with cathepsin B. In vivo, the MMAE conjugate displayed good tolerability and dose-dependent inhibition of tumor growth." (PMID 37239890, 2023). "Furthermore, the WB analysis showed that the expression levels of vimentin, PIAS1, P62, cathepsin B and D, SUMO2/3, SUMO1, and CDC42 were lower in the xenograft tumor tissues of Hct116 and LoVo control cells than in the PDCs." (PMID 37833712, 2023). "Thus, it is not surprising that the use of cathepsin B inhibitors can significantly reduce both metastases and tumour cell invasiveness, as has been already shown in several in vitro studies." (PMID 37233478, 2023). "However, like other cathepsin B inhibitors, it has a limitation in that its anticancer effect is not strong enough to completely suppress the tumor, but its therapeutic efficacy as an anticancer drug candidate is sufficient." (PMID 37111617, 2023). "According to the research findings, cathepsin B digestion reduced the size and overall negative charge of the formulation’s nanoparticles, perhaps allowing for better nanoparticle diffusion into impenetrable tumor tissues after extrusion." (PMID 35903701, 2022). "Additionally, the analyzed CTSB/STFA ratio showed lower values in the tumor samples due to the higher expression of the inhibitor in non-cancerous tissues." (PMID 35563761, 2022). "In summary, they gave the first example of designing and applying cathepsin B response and cell membrane targeting amphiphilic chimeric peptide CTGP, demonstrating how peptide-based self-assembly and cell encapsulation could overcome tumor MDR." (PMID 35186883, 2022). "Thus, our ACPP tumor drug delivery vehicles provide a solution for tumor-targeted localization (MMP 2/9 cleavable linker), intracellular delivery (r9 CPP), and free drug release (cathepsin B cleavable linker)." (PMID 33801967, 2021). "S100A4, cathepsin B, cyclin B1, Annexin A2, S100A10, TRIM21, 14-3-3 ζ/δ, and Ezrin may hence participate in tumor invasion depending on the grade of human CRCs, and protein upregulation during lymph node metastasis also suggests a positive correlation with metastasis in human CRCs." (PMID 32154176, 2020). "Furthermore, we showed that overexpression of CTSB (CTSBwt/hi) but not of an active site mutant CTSB (CTSBN298A) abolished the therapeutic inhibitory effect of TKI on tumor growth." (PMID 30796200, 2019). "Accordingly, a minor fraction of CTSB-overexpressing cells in ParvOryx-treated patients displayed a non-macrophage EGFR-positive phenotype, suggesting that endogenous CTSB induction may also contribute to tumor cell killing." (PMID 28967558, 2017). "Furthermore, CTSB can degrade the basement membrane and ECM for facilitating tumor progression." (PMID 27031837, 2016). "Whether there is a universal link between Rho, caveolin-1, cathepsin B, and acidification of the tumor microenvironment has not yet been evaluated." (PMID 22093547, 2011). "However, targeting cathepsin B alone may not be sufficient to eliminate tumours, and a multifaceted approach targeting multiple molecules or using a combination of chemotherapy or radiation along with targeting cathepsin B may be more appropriate." (PMID 38500921, 2024).
tumor (continued). "Moreover, targeting cathepsin B alone may not be sufficient to eliminate tumours, and a multifaceted approach targeting multiple molecules or using a combination of chemotherapy or radiation along with targeting cathepsin B may be more appropriate." (PMID 38500921, 2024). "The overall expression and enzymatic activity of CTSB in GBM could be regulated through the alternative splicing of the pre-mRNA of CTSB39,40, which determined by the differentiation and microenvironment of tumor cells and in return influence the malignant behavior of GBM39." (PMID 35277559, 2022). "Therefore, cathepsin B which releases to extracellular compartment has a multifaceted effect on tumor cells: activation of cathepsin B on the one hand can hydrolyze ECM and activate matrix metalloproteinases, triggering ECM remodeling, promoting tumor migration and invasion." (PMID 32727598, 2020). "Moreover, sunitinib had no direct effect on tumor cell CTSB expression in vitro." (PMID 30796200, 2019). "Because profound upregulation of CTSB was found in HNSCC tissues compared with paired adjacent normal tissues, CTSB-sensitive NPs were developed to achieve tumor-targeting capacity." (PMID 31805962, 2019). "CTSB was localized in the cytoplasm and cell membrane of IBC tumor emboli and non-IBC carcinoma cells." (PMID 21199580, 2011). "Importantly, treatment with CTSB inhibitor prohibits BDTT and extends survival in orthoptic liver tumor bearing mice independent of primary orthotopic tumor growth." (PMID 37923799, 2023). "This negative relation of CtsB in metastasizing RCC and StfA in paired non-cancer margins may suggest that tumor progression leads to the active changes in CtsB expression with decreased inhibition." (PMID 35563761, 2022). "However, CTSB-positive non-macrophage cells were also detected (arrow) and found to overexpress EGFR (data not shown), which hints at their tumor origin." (PMID 28967558, 2017).
cancer (408 papers, 1994 to 2026). A tumor composed of atypical neoplastic, often pleomorphic cells that invade other tissues. "This novel ET‐CORM is built on a biocompatible iron core, and releases CO upon cleavage by the cancer‐associated protease cathepsin B (CatB)." (PMID 41199686, 2026). "Since STAT3-mediated regulation of cathepsin-B has been implicated in ferroptosis of cancer cells, we next investigated their roles in HT22 neuronal ferroptosis and the action of 8-HANQ." (PMID 41304754, 2025). "Our findings reveal the association between cathepsin B (CTSB) and an elevated risk of developing UL (all cancers excluded) [Inverse Variance Weighted (IVW) method]: OR = 1.06, 95%CI [1.02, 1.11], P = 0.008895711." (PMID 39264885, 2024). "Overexpression of cathepsin B is associated with cancer and cathepsin B-sensitive peptides are widely used as cleavable linkers for the traceless release of therapeutic antibody–drug conjugates, e.g. DS-8201 and Adcetris." (PMID 39092443, 2024). "Elevated levels of cathepsin B are notably associated with poor prognosis and increased aggressiveness in various cancers, positioning it as a potential biomarker for cancer diagnosis and prognosis." (PMID 38500921, 2024). "The protein N-Myc, encoded by the MYCN gene, is associated with an elevated release of proteins, including cathepsin B, which in turn appears to enhance the invasiveness of cancer cells and their resistance to therapies." (PMID 39981299, 2024). "Referring to the effect of MProPow on cathepsin B (cpr-3) expression, the efficacy of almost twenty CTSB inhibitors has been tested in the treatment of various diseases, ranging from cancer to nervous system-associated maladies." (PMID 39064733, 2024). "Aberrant expression/activity of CTSB is frequently associated with malignant tumor progression and metastasis." (PMID 39264885, 2024). "There are several genetic polymorphisms in the CTSB gene whose effects on several cancers have been studied." (PMID 36510340, 2023). "Despite its proven role in mediating cell death, CtsB activity was associated with cancer recurrence, metastasis, shorter survival and poor prognosis." (PMID 37514035, 2023). "The increased CtsB activity inside and outside the cell in cancer suggested the development of therapeutic and diagnostic approaches based on CtsB activity targeting." (PMID 37514035, 2023). "Cathepsin B specific smart prodrug system appeared to be a promising strategy in releasing a protein drug specifically to cancer cells when associated to the CD9 tetraspanin." (PMID 36579638, 2023). "Changes in the level of CTSB expression have been extensively studied and associated with the processes of proliferation, invasion, and metastasis of cancer cells." (PMID 37446393, 2023). "In humans, high OGT levels in TAMs are linked to cathepsin B expression, predicting chemotherapy results and cancer outcomes." (PMID 38116061, 2023). "Cathepsin B is active in an acidic environment and is associated with poor prognosis and the increased aggressiveness of cancer." (PMID 37568601, 2023). "The hotspots identified in this study included CTSB-related cancer and inflammatory diseases, CTSB-associated cell death pattern, and the applications of CTSB." (PMID 35872750, 2022). "The main topics included CTSB-related cancers and inflammatory diseases, CTSB-associated cell death pattern, and the applications of CTSB." (PMID 35872750, 2022). "Owing to the indispensability of the immune system during antiviral processes, the association between the CTSB expression and immune infiltration level in cancer was investigated by TIMER." (PMID 35155389, 2022). "Studies have confirmed that CTSB is a risk factor for tumor cell migration, proliferation, and apoptosis and synchronously affects cancer angiogenesis and chemoresistance." (PMID 36713420, 2022). "Cancers of the breast, cervix, bladder, stomach, colon, ovary, lung, prostate, and thyroid have all been associated with the overexpression of cathepsin B." (PMID 36574159, 2022).
cancer (continued). "And confirmed by genomic and proteomic analysis, many human cancers are associated with high expression of CTSB, such as esophageal cancer, glioblastoma, breast cancer and so on." (PMID 35186883, 2022). "The F68-FDOX induced a potent cytotoxicity preferentially in cancer cells by cathepsin B-specific cleavage mechanism, while maintained the inactive state in cathepsin B-deficient normal cells." (PMID 36195911, 2022). "Because of the widespread association of cathepsin B with serious diseases such as cancer, autoimmune, and neurological diseases, there is a great interest in developing potent and selective CTSB inhibitors for clinical use." (PMID 32979864, 2021). "Matrix metalloproteinases (MMPs) and cathepsin B (CB) are important representatives of proteases associated with cancer." (PMID 33922291, 2021). "Cathepsin B, a lysosomal cysteine protease, is associated with premalignant lesions and invasive stages of cancer." (PMID 31484396, 2019). "Higher CTSB expression was significantly associated with poor survival in the pan-cancer dataset (HR > 1.4)." (PMID 30796200, 2019). "To explore association of CTSB expression with survival across all cancer types, we performed survival analysis using the TCGA database." (PMID 30796200, 2019). "CTSB also regulates cancer stem cells (CSCs), long implicated in drug resistance and progression of cancer." (PMID 30796200, 2019). "Cathepsin B is a lysosomal cysteine protease that has been linked to cancer progression, specifically in signaling pathways related to angiogenesis." (PMID 29740539, 2018). "Cathepsin B activity in cancer progression was initially associated with pericellular initiation of proteolytic cascades and with direct degradation of ECM components." (PMID 30046941, 2018). "The mechanism underlying the promoting effect of cathepsin B on cancer cell migration and invasion has been investigated." (PMID 29455656, 2018). "Cathepsin B is associated in the invasion process in many types of cancer and these data confirmed the essential role of this cathepsin, in contrast to cathepsin L and cathepsin K in GBM invasion." (PMID 28424417, 2017). "In agreement, we found that cancer exosomes promoted cancer-associated inflammation in terms of cathepsin B activity, pro-inflammatory cytokine secretion and proportion of polarized cells in CEEMs." (PMID 27602764, 2016). "CTSB and CTSD were identified to be associated with various cancer types, and we previously showed that CTSB and CTSD play important roles in NPC development and metastasis." (PMID 26995190, 2016). "Nevertheless, increased level of secreted CTSS or CTSB have been shown to be associated with metastasis in other cancer types." (PMID 27802179, 2016). "Targeting proteases such as CTSB that are causal in cancer with conventional small molecule protease inhibitors will be challenging because cysteine cathepsins are crucial housekeeping enzymes that are required for normal cell function throughout the body." (PMID 26562785, 2015). "Proteases such as the cysteine protease cathepsin B have been implicated in the initiation, promotion and dissemination of cancers including IBC." (PMID 22093547, 2011). "Indeed, cathepsin B has been implicated in the pathophysiology of numerous inflammatory diseases and cancer." (PMID 41323645, 2025). "In addition, the observed increased cathepsin B expression in varying histological grades of OSCC further supports its association with cancer progression." (PMID 38500921, 2024). "Similarly, in head and neck cutaneous SCC, the overexpression of cathepsin B has been associated with cancer invasion and metastasis." (PMID 38500921, 2024). "Cathepsin-B is a lysosomal protease constitutively expressed characterized by having either endopeptidase or exopeptidase functions at neutral or acidic pH respectively, this enzyme is overexpressed by cancer cells and often associated with cancer progression." (PMID 37287910, 2023).
cancer (continued). "However, aberrant overexpression of cathepsin B and its enzymatic activity is associated with different pathological conditions, including cancer." (PMID 37514035, 2023). "We provided an overview of the association between CTSB/L and immune cell infiltration, but the specific association needs further experimental evidence due to the predominant immune cells varying from cancer to cancer." (PMID 35155389, 2022). "Many reports underlined the uncontested role of cathepsin B in cancer progression." (PMID 34770912, 2021). "Importantly, survival analysis across 16 major TCGA cancers revealed that CTSB overexpression is associated with low rates of three and five year patient survival rates (P = 2.5e–08, HR = 1.4)." (PMID 30796200, 2019). "Cathepsin B activity has been associated with a number of tumors in humans and experimental animals, making it an attractive avenue for the imaging and possible treatment of cancer." (PMID 18698347, 2008). "Although the association does not persist after multiple testing or Steiger filtering, this finding adds to our understanding of the causal relationship between CTSB of various cathepsins and UL (all cancers excluded) and may herald new therapeutic avenues for individuals affected by this condition." (PMID 39264885, 2024). "The UCNP were modified with Ce6 as photosensitizerand an enzyme responsive peptide which contained 2-cyanobenzothiazolefor reacting with cathepsin B, an important lysosomal cysteine proteasethat is overexpressed in various malignant tumors." (PMID 39960048, 2025). "In cancer research, CTSB is considered one of the most comprehensive therapeutic targets, and CTSB inhibitors are used as anticancer agents." (PMID 40129990, 2025). "The selective cleavage of the Arg-Phe bond by cathepsin B, which is abundant in cancer cells, facilitated the nanoconversion of PTXm from (Ac)FRRF-DTX NPs, demonstrating effective cytotoxic effects." (PMID 40285925, 2025). "The precancerous microenvironment showed significant upregulation of zebrafish orthologues for MMP25 and CTSB, while orthologues for multiple MMPs and CTSs were upregulated in the cancer microenvironment." (PMID 39511408, 2025). "In cancer cells, cathepsin B localizes on the cellular surface, facilitating ECM degradation and orchestrating the protease cascade to guide the invasive front of metastatic cells." (PMID 40861820, 2025). "Analysis of various MSN concentrations revealed distinct effects on the expression of CtsB and CtsD after 24 h of exposure in healthy and cancer cells." (PMID 40943214, 2025). "It was shown that elevated expressions of CTSB are observed in a variety of human diseases, such as cancer, neurodegeneration, and immunological and developmental disorders." (PMID 40411408, 2025). "These first insights into the molecular mechanism of how BEA inhibits human CTSB should help further evaluate BEA as a candidate for cancer therapy." (PMID 40411408, 2025). "The transition areas (II) that encompass both cancer cells and immune cells as defined in the original study exhibit high expression of FTL, CTSB, and HLA-associated genes (e.g., HLA-A, HLA-B, HLA-C), indicating immune infiltration in the TME." (PMID 40033360, 2025). "Simultaneously, due to the clinical significance of the CSTA-CTSB interaction in various cancers, CTSB was selected for protein-protein docking and molecular dynamics simulation." (PMID 40007784, 2025). "The prodrug nanoparticles cleaved and delivered doxorubicin only in cathepsin B-overexpressing cancer cells, leading to cancer cell-specific cytotoxicity." (PMID 40807486, 2025). "Although CTSB often plays a pathological role in diseases such as cancer and neurodegeneration, it also has important physiological functions in normal cells." (PMID 40129990, 2025). "Previous studies reported that CTSB increased levels correlate with cancer progression and metastatic processes." (PMID 41227296, 2025).